TBC1D27P (TBC1 domain family member 27, pseudogene)
Synonyms: formerly TBC1D27
Gene: Transcribed unprocessed pseudogene on chromosome 17 (16,923,996 to 16,932,505, reverse strand). Ensembl gene ENSG00000128438.
Diseases named in the same sentence as TBC1D27P in open-access papers:
TBC1D27P is named in the same sentence as 1 disease in open-access papers, as found by Europe PMC text mining. Sharing a sentence is not in itself a finding about the gene and the disease.
TBC1D27P shares sentences with these, for which no sentence is quoted: B-cell acute lymphoblastic leukemia (1 paper).